PDC (phosducin)
Diseases named in the same sentence as PDC in open-access papers (continued):
Sharing a sentence is not in itself a finding about the gene and the disease.
chlamydial infection (1 paper, 2017). "The role of pDC in chlamydial infection has been controversial." (PMID 29552679, 2017). "To further shed light on the roles of pDC subsets on chlamydial infection, we infected wild type mice intravaginally with C. muridarum, on day 7 post infection, we accessed activated pDC profile from local draining lymph nodes: iLN and infection site: GT by FACS." (PMID 29552679, 2017).
depression (1 paper, 2025). "This fits with clinical observations: patients receiving long-term interferon-α treatment, which reproduces a high interferon state, often develop depressive symptoms or MDD, and altered pDC function has also been described in depression." (PMID 41280439, 2025).
Ewing`s sarcoma (1 paper, 2019). "For instance, the hY1R-overexpressing Ewing`s sarcoma cell line SK-N-MC was much more affected by the PDC than the normal (but chemically transformed) cell line 184B5 with weak hY1R expression." (PMID 30680044, 2019).
familial hypercholesterolemia (1 paper, 2022). An inheritable form of hyperlipidemia, in which there are excess lipids in the blood. "However, we await future studies of pDC function and phenotype in patients with familial hypercholesterolemia." (PMID 35625889, 2022).
Granuloma (1 paper, 2016). A compact, organized collection of mature mononuclear phagocytes, which may be but is not necessarily accompanied by accessory features such as necrosis. "Pulmonary lesions in pDC-sufficient mice replaced large part of normal tissue and were composed of organized granulomas of small sizes although in higher number and containing a higher number of yeasts cells than those found in the pDC-depleted mice." (PMID 27992577, 2016).
gynecological cancers (1 paper, 2022). "The current study highlights the TH1902 anticancer properties, a new PDC against gynecological cancers." (PMID 35454785, 2022).
heart failure (1 paper, 2024). Inability of the heart to pump blood at an adequate rate to meet tissue metabolic requirements. "Recent research has shown that in patients with heart failure before cardiac resynchronization therapy (CRT), there is a lower frequency of pDC, which increases CD86 expression post-CRT." (PMID 39421157, 2024).
Hepatitis (1 paper, 2010). Inflammation of the liver. "Furthermore, other endemic chronic infections such as HIV, hepatitis and tuberculosis, are not likely to underlie the selective dysfunction of mDC either, since in contrast to our findings, these types of infections have been found to be associated with functional impairment of pDC." (PMID 20422029, 2010).
HSV keratitis (1 paper, 2020). "As expected, pDC depletion was associated with a markedly attenuated IFN-a response to HSV infection on day 3, at both mRNA and protein levels, suggesting that corneal IFN-α secretion during acute HSV keratitis is largely pDC dependent." (PMID 32877681, 2020). "The observed higher rate of death upon pDC depletion in acute HSV keratitis can be explained by enhanced viral dissemination to extra-ocular tissues, resulting in the spread of the virus to the central nervous system and subsequent death." (PMID 32877681, 2020).
IgA nephropathy (1 paper, 2017). "In conclusion, pDC and its secreted cytokine IFN-α may play important roles in pathological changes of IgA nephropathy." (PMID 29403161, 2017). "The roles of pDC and IFN-α have not been well defined in IgA nephropathy (IgAN)." (PMID 29403161, 2017).
keratitis (1 paper, 2020). A corneal disease that is characterized by inflammation of the cornea. "Clinical keratitis severity, judged by the degree of corneal opacification, was markedly exacerbated in pDC-depleted mice as early as day 3 p.i.." (PMID 32877681, 2020).
Klebsiella pneumonia (1 paper, 2013). An pneumonia caused by infection with Klebsiella. "Unexpectedly, with respect to pDC representing the rarest subset, we found a marked relative and absolute elevation of respiratory pDC numbers in the post acute phase of Klebsiella pneumonia (d5 p.i.)when compared to mock-infected controls (p < 0.01)." (PMID 24044871, 2013).
liver disease (1 paper, 2008). "By inoculating N. aromaticivorans to mice, we established a model of liver disease resembling PBC and we further demonstrated the role of NKT cells in initiating a liver-specific autoimmune process mediated by T cells as well as in helping the production of signature anti-PDC E2 antibodies." (PMID 18474357, 2008).
lung carcinoma (1 paper, 2023). "There is an increased pDC in the TME of smokers’ lung cancer, and the response of pDC to DNA damaging treatment would lead a conducive environment to ICIs containing regimens." (PMID 37435086, 2023).
lupus nephritis (1 paper, 2021). Glomerulonephritis in the context of systemic lupus erythematosus. "Interestingly, we found that IL-33 NETs were predominantly localized within the tubulointerstitium, and tubulointerstitial inflammation has been correlated with pDC infiltrates and poor prognosis in lupus nephritis." (PMID 34554930, 2021).
lymph node metastasis (1 paper, 2021). "Significant increased tumor-infiltrating pDC was seen in carcinoma tissues of OSCC patients with lymph node metastasis (OSCCLN(+)) compared to that of without lymph node metastasis (OSCCLN(-) )." (PMID 33854604, 2021).
lymphadenitis (1 paper, 2025). Acute or chronic inflammation of one or more lymph nodes. "In this line, a previous study associated pDC redistribution and clustering with a worse HIV prognosis, specifically, with lower CD4+ T cell counts and advanced HIV‐lymphadenitis stage." (PMID 40949488, 2025).
lymphopenia (1 paper, 2021). Reduction in the number of lymphocytes. "According to the observed lymphopenia, symptomatic hospitalized patients had a very and consistently low level/depletion of circulating pDC independently of their age and sex." (PMID 34473805, 2021).
male infertility (1 paper, 2026). The inability of the male to effect fertilization of an ovum after a specified period of unprotected intercourse. "This study provides suggestive genetic evidence that pDC-mediated glutamate catabolism may connect gut microbial metabolic activity to male infertility." (PMID 41650037, 2026).
medulloblastoma (1 paper, 2024). A malignant, invasive embryonal neoplasm arising from the cerebellum. "Furthermore, we identified retina specific interphotoreceptor matrix proteoglycan 2 (IMPG2), phosducin (PDC) and prominin 1 (PROM1) as upregulated genes in the RB tumor group, which are all related to CRX expression in medulloblastoma." (PMID 39695086, 2024).
metastatic disease (1 paper, 2024). "The study found that patients with high levels of pDC, NSCLC in stages I to III, and without metastatic disease, had better OS than patients with low pDC levels, with a mean OS of 30.4 versus 20.7 months (P = 0.013)." (PMID 39308861, 2024).
myeloid neoplasm (1 paper, 2024). Proliferation of myeloid cells originating from a primitive stem cell. "However, recent studies have broadened our understanding of neoplastic pDC proliferation in association with myeloid neoplasms outside the context of BPDCN, that is, AML with pDC differentiation (pDC-AML)." (PMID 38893237, 2024). "Thus, a flow cytometry panel with core pDC markers is recommended for the evaluation of myeloid neoplasms." (PMID 38893237, 2024). "Myeloid neoplasms may undergo pDC differentiation, most commonly seen in AML (pDC-AML)." (PMID 38893237, 2024).
oral cancer (1 paper, 2021). "In the present study, we collected clinicopathological data and follow-up information from 122 OSCC patients to confirm the predicted role of tumor-infiltrating pDC in oral cancer LN metastasis." (PMID 33854604, 2021). "However, it has yet to be clearly established which factors have an important role in pDC-CM-mediated NF-κB activation in oral cancer." (PMID 33854604, 2021). "Next, the impact of tumor-infiltrating pDC on oral cancer cell was investigated." (PMID 33854604, 2021). "Careful manipulation of these impaired tumor-infiltrating pDC may help develop an important alternative immunotherapy for oral cancer." (PMID 33854604, 2021). "ELISA results showed that the concentration of TNF-α in LN+ pDC-CM was higher than that in LN- pDC-CM, suggesting that TNF-α secreted by tumor-infiltrating pDC may contribute to NF-κB activation in oral cancer cells." (PMID 33854604, 2021).
periodontitis (1 paper, 2024). An acute or chronic inflammatory process that affects the tissues that surround and support the teeth. "In addition, our study identified a convoluted causal relationship between pDC and periodontitis." (PMID 38536078, 2024). "The involvement of pDC in periodontitis deserves further investigation." (PMID 38536078, 2024). "Notably, four of these high-confidence genes were found to be involved with multiple phenotypes: S100A9, S100A12 (neutrophils and periodontitis); MCM6, P14KAP2 (neutrophils and pDC)." (PMID 38536078, 2024).
pneumonia (1 paper, 2008). An acute, acute and chronic, or chronic inflammation focally or diffusely affecting the lung parenchyma, caused by an infection in one or both of the lungs (by bacteria, viruses, fungi, or mycoplasma.). "A previous study has also demonstrated enhanced number of pDC count in bronchoalveolar lavage fluid of immunocompetent patients with pneumonia." (PMID 18828896, 2008).
Psoriasiform dermatitis (1 paper, 2018). A skin abnormality characterized by redness and irritation, with thick, red skin that displays flaky, silver-white patches (scales). "The role of pDC and IFN-I in the IMQ psoriasiform dermatitis model is controversial in addition to the source of IFN-I production." (PMID 30262916, 2018).
rosacea (1 paper, 2023). A chronic erythematous skin disorder that affects the face. "However, some residual IFN-β and IFN-response gene expression are discernible, despite pDC-depletion, and skin of chronic stabilized rosacea shows a diffuse MxA-staining pattern." (PMID 36633910, 2023). "We asked what the pathomechanism underlying the enhanced pDC activation and type I IFN production in rosacea could be." (PMID 36633910, 2023). "Using both in vitro and in vivo models, we demonstrate that commensal skin bacteria are necessary for pDC activation and type I IFN production, which, in rosacea, is further amplified by dysbiotic bacteria and AMPs with increased type I IFN–inducing capacities." (PMID 36633910, 2023).
scrub typhus (1 paper, 2021). Scrub typhus is a rare dust mite-borne infectious disease caused by the Orientia tsutsugamushi bacterium and characterized clinically by an eruptive fever which is potentially serious. "To evaluate the clinical relevance of pDC and cDC levels in 35 patients with scrub typhus, we investigated the correlation between pDC and cDC percentages in the peripheral blood and clinical parameters by Spearman’s rank correlation analysis." (PMID 34276693, 2021). "Circulating pDC and cDC levels were found to be significantly reduced in scrub typhus patients, which were correlated with disease severity." (PMID 34276693, 2021).
skin cutaneous melanoma (1 paper, 2023). "pDC signature resulted poorly expressed in skin cutaneous melanoma (TCGA-SKCM) as compared to primary carcinomas (TCGA-BLCA, TCGA-COAD, TCGA-HNSC, TCGA-LUAD, TCGA-LUSC)." (PMID 38239354, 2023).
skin inflammation (1 paper, 2017). "Cutaneous IFN- α RNA expression levels were determined at days 1 and 3 of IMQPD to detect a signature for the functional contribution of skin-infiltrating pDC to the early development of skin inflammation." (PMID 28777803, 2017).
toxoplasmosis (1 paper, 2022). A parasitic disease contracted by the ingestion or fetal transmission of toxoplasma gondii. "Together, these results highlight a stronger disease course of Toxoplasmosis with increased numbers of neutrophils, pDC activity, and effector T cell IFNγ production, all known to strongly influence the severity of diseases." (PMID 35898505, 2022).
Yersinia infection (1 paper, 2013). "The B. adolescentis-mediated protection from Yersinia dissemination to the spleen was abrogated after plasmacytoid dendritic cell depletion indicating a crucial function for pDC in control of intestinal Yersinia infection." (PMID 23977019, 2013).
tumor (124 papers, 2008 to 2025). "Our previous data have demonstrated that pDC infiltration is associated with GBM tumor immunosuppression as well as a poor outcome, and selective pDC depletion increases the survival of tumor-bearing mice." (PMID 39456552, 2024). "These underlying pDC–tumor cell interactions should be further confirmed to develop a complete picture of direct pDC–tumor cell crosstalk." (PMID 37817484, 2023). "In PDAC, cDC1 and pDC infiltration in the tumor and tumor stroma was associated with better prognosis." (PMID 36726981, 2022). "The analysis of ILC3 versus pDC DEGs showed that many tumor ILC3 DEGs were involved in RNA degradation, metabolic, and apoptotic pathways, whereas most tumor pDC DEGs were associated with tumor development or inhibition." (PMID 33708200, 2021). "We found marked increases in tumor burden in three distinct B cell-deficient mouse models—including muMT mice after pDC depletion—and after B cell-derived NAb depletion." (PMID 34608861, 2021). "Activated pDC contribute to cross-presentation of tumor-associated antigens by classical dendritic cells, which induce cytotoxic T-cells in particular in the presence of checkpoint inhibitors." (PMID 31083559, 2019). "The presence of immature pDC in these tumors is regularly associated with an immunosuppressive microenvironment, promoting regulatory immunity, and favoring tumor progression." (PMID 31083559, 2019). "Several authors have proposed that tumor-associated pDC provide a co-stimulation signal and induce Treg expansion through ICOS-L-ICOS interaction." (PMID 30979057, 2019). "Researchers have also confirmed that tumor-associated pDC strongly correlated with Tregs and that tumor-associated pDC altered functionality (loss of IFN-α secretion) was associated with Foxp3 +Tregs accumulation within BC." (PMID 24124553, 2013). "We demonstrated that human pDC can cross-present a tumor-associated antigen (NYESO-1) to CD8+ T cells from the MV-infected tumor cells." (PMID 24832799, 2013). "Similarly, in mouse models of breast cancer bone metastasis, pDC depletion resulted in an overall decreased tumor burden and bone loss via the activation of CD8+ T cells and a Th1-oriented immune response." (PMID 38504978, 2024). "Tumor infiltration by plasmacytoid dendritic cells is already well described and is associated with poor outcomes in cancers due to the tolerogenic activity of pDC." (PMID 35884612, 2022). "The analysis of DEGs in ILC3s versus pDCs revealed that most upregulated and downregulated ILC3 genes were associated with RNA degradation, metabolic, and apoptotic pathways, whereas most upregulated and downregulated pDC genes were associated with tumor development or inhibition." (PMID 33708200, 2021). "Therefore, pDC represent good candidates for therapy targeting tumor-associated DC to boost anti-tumor immunity." (PMID 30979057, 2019). "According to the role of DCs in tumor metabolism, they can be classified into three subtypes: cDC1, cDC2, and pDC (plasma cell-like DCs), and have a role in anti-tumor effects, tumor progression, and metastasis." (PMID 40696413, 2025). "Studies have shown that impaired pDC functions correlate with poor prognosis in HCC patients, underscoring the importance of strategies to restore or enhance pDC’s anti-tumor activity in HCC as a potential therapeutic approach." (PMID 40432108, 2025). "The interplay between upregulated metabolic genes and downregulated pancreatic secretion genes in PDC highlights a major shift towards tumor-driven metabolic adaptation and immune evasion." (PMID 40226632, 2025). "This PDC exhibited remarkable selectivity and anti-tumor efficacy in SSTR2-overexpressing cell lines, including IMR32, CFPAC-1, MOLT-4, and PC-3." (PMID 40428099, 2025). "The heat map results showed that in most cancers, TUBA1B expression was negatively correlated with pDC but significantly positively correlated with tumor-promoting Th2 cells." (PMID 38589634, 2024).